LRATD2 (LRAT domain containing 2)
Synonyms: BCMP101; FAM84B; NSE2
Tractability: Antibody: its Gene Ontology location is reachable by antibodies, with high confidence. PROTAC: ubiquitination databases record sites on it.
Gene: Protein-coding gene on chromosome 8 (126,552,443 to 126,558,478, reverse strand). Ensembl gene ENSG00000168672.
Subcellular location (Human Protein Atlas): Nucleoplasm
Gene Ontology:
Molecular function: protein binding
Cellular component: cytoplasm; plasma membrane
Genetic constraint (gnomAD): Loss-of-function variants: 15 observed, 14.21 expected, observed/expected ratio (o/e) 1.06, 90% interval 0.7 to 1.61. The upper end of that interval is the gene's LOEUF score, 1.61, which puts it in group 6 of 6, group 1 being the genes least tolerant of losing a copy. Missense variants: 455 observed, 439.25 expected, observed/expected ratio (o/e) 1.04, 90% interval 0.96 to 1.12. Synonymous variants: 220 observed, 202.12 expected, observed/expected ratio (o/e) 1.09, 90% interval 0.97 to 1.22.
Homologues: Orthologues: chimpanzee LRATD2 (100% identical), macaque LRATD2 (98% identical), pig LRATD2 (95% identical), mouse Lratd2 (93% identical), rat Lratd2 (93% identical), guinea pig LRATD2 (91% identical), dog LRATD2 (90% identical), rabbit LRATD2 (87% identical), tropical clawed frog lratd2 (61% identical), zebrafish lratd2a (56% identical), zebrafish lratd2b (54% identical). Paralogues in human: LRATD1 (42% identical), PLAAT2 (15% identical), PLAAT3 (15% identical), PLAAT5 (14% identical), PLAAT4 (14% identical), LRAT (13% identical), PLAAT1 (12% identical).
Diseases named in the same sentence as LRATD2 in open-access papers:
LRATD2 is named in the same sentence as 30 diseases in open-access papers, as found by Europe PMC text mining. Sharing a sentence is not in itself a finding about the gene and the disease. The quoted sentences say what the papers report.
prostate carcinoma (10 papers, 2017 to 2024). A carcinoma that arises from epithelial cells of the prostate gland. "The expression of FAM84B/LRATD2 is up-regulated during prostate cancer progression and in preclinical and esophageal squamous cell carcinoma tumors." (PMID 34433667, 2021).
breast carcinoma (9 papers, 2009 to 2024). "The data show an upregulation of breast cancer related genes in T1 and C1 relative to 10A, including LRATD2, PCAT1, CASC19, CASC8, POU5F1B, PVT1 and MYC on chromosome 8." (PMID 38076897, 2024).
glioma (5 papers, 2021 to 2025). A benign or malignant brain and spinal cord tumor that arises from glial cells (astrocytes, oligodendrocytes, ependymal cells). "Likewise, in the comparison of the control and the CP group, the significantly upregulated LRATD2 is the main inducer of neuroendocrine tumor, which induces glioma by the cell cycle or Akt/GSK-3β/βpathways." (PMID 38891594, 2024).
tumor (15 papers, 2009 to 2024). "LRATD2 (FAM84B) had the highest abundance (fragments per kilobase of exon per million mapped reads) in PCa, and its expression was most significantly elevated in tumor tissues compared to normal tissues." (PMID 38997648, 2024).
LRATD2 also shares sentences with these, for which no sentence is quoted: cancer (19 papers); esophageal squamous cell carcinoma (9); pancreatic ductal adenocarcinoma (3); esophageal cancer (2); melanoma (2); neuroendocrine carcinoma (2); neuroendocrine tumor (2); prostate tumors (2); Alzheimer disease (1); amyloidosis (1); benign meningioma (1); benign tumors (1); breast tumor (1); gastric cancer (1); gastroesophageal junction adenocarcinoma (1); hepatocellular carcinoma (1); Huntington disease (1); intraepithelial neoplasia (1); liver disease (1); malignant glioma (1); meningioma (1); metastatic disease (1); pancreatic cancer (1); Parkinson disease (1); prostate adenocarcinoma (1); tuberculosis (1).